MAD1L1 (mitotic arrest deficient 1 like 1)
Diseases named in the same sentence as MAD1L1 in open-access papers (continued):
Sharing a sentence is not in itself a finding about the gene and the disease.
leukemia (1 paper, 2025). A malignant (clonal) hematologic disorder, involving hematopoietic stem cells and characterized by the presence of primitive or atypical myeloid or lymphoid cells in the bone marrow and the blood. "As expected, several previously reported genes with abnormal methylation in leukemias such as CPEB1, BLK, FLT3, ZCCHC7, EBF1, HDACs, IKZF1, RB1, CDK6, DOCK5, DPP10, MUC4, JAKs, KIT, KRAS, LINC01013, MAD1L1, NOTCH1, and STATs, among others, were also detected." (PMID 41226303, 2025).
metastatic disease (1 paper, 2022). "Although the role of MAD1L1 in cancer has not been fully elucidated, some studies suggest loss of expression is associated with metastatic disease and poor prognosis." (PMID 36344544, 2022).
multiple sclerosis (1 paper, 2023). A progressive autoimmune disorder affecting the central nervous system resulting in demyelination. "However, looking into our phenotypic data we can verify that CTD (SLC22A5), Parkinson ́s disease (LRPPRC), multiple sclerosis (IL4R), 3-MCCD (MCCC1), and different cancer types (FANCE, MAD1L1 and CD46) have been reported by the participants." (PMID 36404349, 2023).
myeloid tumor (1 paper, 2024). "In human U-937 myeloid tumor cells, knockdown of MAD1L1 inhibited TGF-beta-induced senescence." (PMID 38412321, 2024).
Neurodevelopmental delay (1 paper, 2022). "Several of the associated genes, including MAD1L1, CAMTA1, and ALDH1A2 have been implicated in neurodevelopmental delay, suggesting that differential DNAm may partly explain the biological mechanisms underlying the relationship between PTE and PAE and child neurodevelopment." (PMID 36180424, 2022).
rhabdomyosarcoma (1 paper, 2023). A rare aggressive malignant mesenchymal neoplasm arising from skeletal muscle. "Tumor predisposition has been observed in patients with biallelic LoF of BUB1B, TRIP13, and MAD1L1, with resulting elevated risks for rhabdomyosarcoma, Wilms tumor, and a variety of malignancies, respectively." (PMID 37796616, 2023).
Sepsis (1 paper, 2024). Sepsis is defined as life-threatening organ dysfunction caused by a dysregulated host response to infection. "Clustering based on the expressions of TGFBI and MAD1L1 was significantly associated with sepsis characteristics and prognoses (all P < 0.05)." (PMID 38412321, 2024). "In our study, we reported for the first time that TGFBI and MAD1L1 could act as diagnostic and prognostic biomarkers in sepsis, and their association with cellular senescence of monocytes and B cells." (PMID 38412321, 2024). "Our findings show that targeting TGFBI and MAD1L1, given their close association with monocytes and B cells, could be promising therapeutic options for sepsis." (PMID 38412321, 2024). "The present study established a gene signature related to cellular senescence that included TGFBI and MAD1L1 to evaluate the prognosis and the occurrence in sepsis." (PMID 38412321, 2024). "We analyzed the expression levels of TGFBI and MAD1L1 in both the control and sepsis samples." (PMID 38412321, 2024). "Subsequently, we conducted GSEA after dividing the monocytes or B cells from sepsis samples into low- and high-expression subgroups based on the median expression level of TGFBI or MAD1L1." (PMID 38412321, 2024).
small cell lung carcinoma (1 paper, 2024). Small cell lung cancer (SCLC) is a highly aggressive malignant neoplasm, accounting for 10-15% of lung cancer cases, characterized byrapid growth, and early metastasis. "Interestingly, copy number gains involving this genomic region known to harbor oncogenes such as UNCX, FAM20C, MAD1L1 and PDGFA have been reported during the immortalization process of patient-derived small cell lung cancer lines." (PMID 39737401, 2024).
ulcerative colitis (1 paper, 2023). An inflammatory bowel disease involving the mucosal surface of the large intestine and rectum. "MAD1L1 differential methylation has additionally been seen at the gut level, within intraepithelial cells in ulcerative colitis." (PMID 37331566, 2023).
cancer (23 papers, 2008 to 2025). A tumor composed of atypical neoplastic, often pleomorphic cells that invade other tissues. "MAD1L1 was hypermethylated in our study, and in previous studies methylation of MAD1L1 was negatively associated with cancer incidence." (PMID 39164771, 2024). "In some studies, the polymorphism in the MAD1L1 rs1801368 T allele has been found to be associated with certain kinds of cancer that showed somatic cell aneuploidy." (PMID 37007941, 2023). "MAD1L1 is a well-studied cell cycle checkpoint gene with mutations implicated in multiple types of cancer." (PMID 26039411, 2015). "Mutations in MAD1L1 have been found in cancers of prostate, breast, brain and lungs and over expression of wt-MAD1L1 is known to inhibit cell growth, thus suggesting a tumor suppressor function of MAD1L1." (PMID 25781993, 2015). "MAD1L1, whose dysfunction is associated with chromosomal instability, plays a pathogenic role in some human cancers and may be involved in cancer progression and metastasis." (PMID 29796160, 2018). "MAD1L1 is a component of the mitotic spindle-assembly checkpoint, and its mutations are suggested to play a role in the pathogenesis of various types of human cancer." (PMID 19607652, 2009). "MAD1L1 may play a pathogenic role in various types of human cancer including HCC." (PMID 33109182, 2020). "The genotypic polymorphisms of MAD1L1 and MAD2L1 genes significantly increased the risk of certain cancers." (PMID 37007941, 2023). "Mutation frequencies of the SAC genes remained low, and only rare polymorphisms in MAD1L1, MAD2L1, and BUB1b were found in certain cancers involved in the modulation of the cell cycle arrest." (PMID 37007941, 2023). "The fusion protein RARS-mitotic arrest deficient 1-like 1 (MAD1L1) activated the FBP/c-Myc pathway by interacting with AIMP2, thereby inducing cancer stem cell-like phenotypes." (PMID 33330488, 2020). "Chromosomal region 7p22 is located in a fragile sequence (FRA7B) containing two miRNA genes (mir589 and mir339) and three large genes (SDK1, THSD7A, MAD1L1), and is highly prone to gaps and breaks in several cancers." (PMID 23626673, 2013). "Initially, qRT-PCR analysis confirmed the RNA interference by siRNA targeting CDK5RAP2, MAD1L1, and RGCC (p< 0.05) in the COAD-derived cancer cell lines of HCT116 and SW480." (PMID 38143740, 2023). "Based on the online Cancer Biobank database, the mRNA expression of MAD1 (the gene homologous to humans was MAD1L1) in CRC tissues (n=275) was higher than that in the control group (n=349)." (PMID 37325046, 2023). "Changes in MAD1L1 and MAD2L1 levels were detected in many cancer cell lines and tumor biopsy samples." (PMID 37007941, 2023). "Ingenuity pathway analysis revealed that differentially methylated CpG sites were annotated to genes involved in ‘cell cycling’ (e.g. NDRG1, NEDD1, and MAD1L1), ‘inflammatory diseases’ (e.g. PRTN3), and ‘cancer’ (PCDHA6, MUC4, and ATP2C2)." (PMID 28754985, 2017). "Changes in MAD1L1 and MAD2L1 may serve as biomarkers for cancer as a potential strategy during anti-cancer treatment." (PMID 37007941, 2023).
tumor (23 papers, 2009 to 2025). "Multiple statistically significant methylation sites were identified in MAD1L1, encoding a protein involved in the mitotic spindle assembly, chromosome alignment, cell cycle control and tumour suppression." (PMID 37239390, 2023). "Our results suggest that MAD1L1 is a tumor suppressor in the context of BRCA1/2 mutation-associated tumors, loss of which is associated with recurrent disease." (PMID 36344544, 2022). "Univariate analysis using the logistic regression model showed that the high expression of PTTG2 and RAD21 was significantly associated with tumor relapse, while low expression of MAD1L1 was associated with tumor relapse (P values < 0.05 for all cases)." (PMID 32596342, 2020). "The list included the genes MAD1L1, HECW1, and ANKIB1, which have been reported to be involved in mitotic checkpoint control and have been previously implicated in tumor progression." (PMID 40722723, 2025). "PTPRN2, a gene involved in insulin secretion, and MAD1L1, which plays a role in the cell cycle and tumor suppression, contained DMRs in males and females in both cohorts." (PMID 35500004, 2022). "For MAD1L1, a gene involved in control of the cell cycle and tumour suppression, four DMRs were found in male neonates and two were found in female neonates." (PMID 35500004, 2022). "As MAD1L1 is known to be involved in neoplasia, further investigation of this cell line can provide a source of comparative studies and shed light on de-regulation of cell proliferation in avian species." (PMID 19607652, 2009). "MAD1L1 involved in tumor suppression and cell cycle control." (PMID 34481484, 2021). "MAD1L1 is located at human chromosome 7q22.3 and involves cell cycle control and tumor suppression." (PMID 34481484, 2021). "AR represses MAD1L1, which functions as tumor suppressor to positively influence proliferation." (PMID 25781993, 2015). "MAD1L1 may play a role in cell cycle control and tumor suppression." (PMID 40353861, 2025). "Furthermore, we detected the mRNA expression level of these hub genes in our frozen tissues and found that FAM174B, MAD1L1, MFSD12, SLC45A2, and TBC1D16 were significantly upregulated in freshly frozen tumor tissues." (PMID 30385854, 2019).
psychiatric disorder (5 papers, 2018 to 2023). A disorder characterized by behavioral and/or psychological abnormalities, often accompanied by physical symptoms. "It is noteworthy that previous studies have identified numerous genetic variants within MAD1L1 that have been linked to psychiatric disorders." (PMID 37920543, 2023). "Previous studies identified multiple genetic variants in MAD1L1 that were associated with psychiatric disorders." (PMID 36600305, 2023). "Intriguingly, MAD1L1 has also been implicated in the genetic susceptibility to schizophrenia, another psychiatric disease sharing substantial risk factors with BPD." (PMID 30531795, 2018). "Together, these findings suggest that specific methylation profiles within MAD1L1 may be regarded as a risk factor for PTSD in addition to several other psychiatric disorders." (PMID 31931860, 2020).
neurodevelopmental disorder (2 papers, 2022). A behavioral and cognitive disorder with onset during the developmental period that involves impaired or aberrant development of intellectual, motor, or social functions. "PTPRN2, MAD1L1, and AGAP1 are all linked to neurodevelopmental disorders and associate significantly with PAE or FASD in two or more previous genome-wide DNAm studies." (PMID 36581877, 2022). "Previous studies have found that maternal smoking was associated with a higher rate of SZ and BPD in offspring, suggesting that differential expression of MAD1L1 may be a plausible pathway that links smoking to neurodevelopmental disorders." (PMID 36180424, 2022).
cardiovascular disease (1 paper, 2024). "Additionally, emerging research has found MAD1L1 to be a potential candidate gene for cardiovascular disease." (PMID 39695878, 2024).
MAD1L1 also shares sentences with these, for which no sentence is quoted: Anxiety (3 papers); adult T-cell leukemia (1); anxiety disorder (1); autism (1); behavioral disorder (1); emphysema (1); epilepsy (1); Failure to thrive (1); gastric cancer (1); head and neck squamous cell carcinoma (1); immune diseases (1); insomnia (1); ischemia reperfusion injury (1); Joubert syndrome 23 (1); lung adenocarcinoma (1); lymphoma (1); neurological disorders (1); osteoarthritis (1); ovarian carcinoma (1); pancreatic adenocarcinoma (1); Parkinson ́s disease (1); rheumatoid arthritis (1); type 1 diabetes (1); Wilms tumor (1).